KRAS (KRas proto-oncogene, GTPase)
Diseases named in the same sentence as KRAS in open-access papers (continued):
Sharing a sentence is not in itself a finding about the gene and the disease.
colon carcinoma (continued). "KRAS mutations are associated with a shorter DFS and OS in patients with MSI-L tumors, which represent approximately 90% of all stage III colon cancer but have no prognostic implication in patients with MSI-H tumors." (PMID 30736475, 2019). "Characteristics of colon cancer patients and tumors according to BRAF and KRAS status." (PMID 29568398, 2018). "Compared with colon cancer rectal cancer, KRAS/NRAS/BRAF have a lower mutation rate in gastric cancer, furthermore, there is no consistent conclusion on the role of KRAS/NRAS/BRAF mutations in gastric cancer." (PMID 30416987, 2018). "Consistent with preclinical studies, increased levels of HGF in colon cancer patients with WT KRAS, and in NSCLC patients correlate with lack of response to EGFR inhibitors." (PMID 28420162, 2017). "Roth et. al reported that KRAS exon 2 mutation was related to tumor grade and MSI status in stage II-III colon cancers, but RAS mutations were not related to tumor grade or dMMR status in our series." (PMID 28416767, 2017). "Indeed we observed the same mechanism in three patient-derived colon cancer cell lines carrying BRAFV600E (Pt-1), KRASG13 (Pt-3) and wt BRAF and KRAS (Pt-2)." (PMID 29312543, 2017). "Though the relevance of the MEK-ERK and PI3K-AKT signaling pathways to MUC2 gene expression has been previously shown in colonic goblet cells and in colon cancer cells, the relevance of KRAS oncoprotein to MUC2 gene expression has not been directly assessed." (PMID 28640835, 2017). "In a study of 69 patients with KRAS exon 2 mutant CRC, IGF-1 expression was higher in rectal than colon tumors, approaching statistical significance (P = 0.06) and suggesting that rectal cancers harbor oncogenic pathways that are different from colon cancers." (PMID 29156800, 2017). "To explore how different mutations change the response of tumor cells to drugs we treated CaCO2 (wildtype for BRAF and KRAS), HCT116 (KRASG13D), and HT29 (BRAFV600E) colon carcinoma cells with the MEK inhibitor AZD6244 or with the RAF inhibitor Sorafenib for various periods of time." (PMID 26799289, 2016). "The results showed that the expression of both KRAS and XPi2 was significantly reduced in colon carcinoma compared with that in the matched non-tumor tissues." (PMID 27880931, 2016). "In the present study, the effect of KRAS/BRAF/PIK3CA oncogenic pathways on the autophagic cell properties and on main components of the autophagic machinery like p62 (SQSTM1), Beclin-1 (BECN1) and MAP1LC3 (LC3) in colon cancer cells was investigated." (PMID 26802026, 2016). "Nelfinavir also sensitized NRAS mutant melanoma cells to MEK inhibition and reduced PAX3 and MITF expression, whereas no sensitization was seen in the KRAS mutant colon cancer cell line HCT116." (PMID 26977879, 2016). "In this study, we systematically interrogated the effect of inhibiting MEK and RAF on both MAPK signalling and AKT signalling in various colon cancer cell lines with and without mutations in BRAF and KRAS." (PMID 26799289, 2016). "KRAS, BRAF and NRAS mutations do not have major prognostic value in stage II and III colon cancer, subtypes of gene mutations should be further investigated for a better understanding in CRC." (PMID 27074743, 2016). "In our reporter assay, ~3 μM TMPyP4 incubated with cells for 72 h after transfection reduced human KRAS promoter activity by 25% but did not inhibit KRAS transcription in colon cancer HCT116 cells at a 12 μM concentration." (PMID 25853628, 2015).
colon carcinoma (continued). "The Raman results show that colon cancer cells experience a large spectral response to erlotinib, but colon cancer cells expressing oncogenic BRAF or KRAS mutations experience small or no relevant effects, respectively." (PMID 26168967, 2015). "While reovirus has demonstrated increased oncolytic activity in KRAS activated cells, the efficacy of the virus has not been comprehensively tested in colon cancer cells." (PMID 24798549, 2014). "A spurious band which has never been described in the literature appeared in the KRAS western blot of the normal colon cancer tissue." (PMID 25287248, 2014). "Given that gene mutations (KRAS, BRAF and PIK3CA) influence cetuximab sensitivity, we chose two cell lines (Caco-2 and DiFi) that express wild-type KRAS, BRAF and PIK3CA, paralleling the molecular features of colon cancer patients who are most likely to respond to cetuximab." (PMID 24714091, 2014). "Interestingly, in spite of a tremendous amount of available literature on biomarkers in CRC, only a few biomarkers are nowadays used in daily clinical practice, such as KRAS, BRAF, MSI and the Oncotype DX® Colon Cancer Assay." (PMID 24759962, 2013). "In line with our previous observation, synergistic activity was only observed in HT-29 and RKO cell lines, which have wild-type KRAS genes, and not in HCT116, DLD-1, and other colon cancer cell lines with mutant KRAS genes (data not shown)." (PMID 23555026, 2013). "ISC-4 in combination with cetuximab synergistically reduced the viability of human colon cancer cells with wild-type but not mutant KRAS genes." (PMID 23555026, 2013). "Most characteristics were similar between KRAS groups, although the MT KRAS PRO population included proportionally more women (20% vs. 46%), elderly patients (≥75 years of age; 7% vs. 19%) and patients with colon cancer (57% vs. 67%) compared with the WT population." (PMID 23020584, 2012). "N0147 randomized 1760 patients with resected stage III KRAS WT colon cancer to FOLFOX with or without cetuximab." (PMID 21437184, 2011). "In the Cox regression analysis, only when colon and rectal cancer were analysed separately, KRAS mutation was a negative predictor for OS in patients with rectal cancer and DFS in those with stage II colon cancer." (PMID 20959826, 2010). "Activation of Akt in hypoxia appears to be a common feature of colon tumors with or without KRAS mutations, but it has become clear that mutant K-ras and physiologically activated wild-type K-ras do not function identically." (PMID 20532039, 2010). "The KRAS mutation also serves as a strong predictor of non-responsiveness to EGFR–targeted agents in lung and colon cancers." (PMID 21124782, 2010). "The KRAS mutation came forward as a negative predictive factor for OS in patients with rectal cancer and for DFS in stage II colon cancer patients." (PMID 20959826, 2010). "To determine if pharmacological inhibition of USP25 is effective in reducing the expression levels of KRAS protein and in tempering KRAS signaling, we treated HT29 colon cancer cells (which do not harbor mutations in KRAS) with different concentrations of CT1113." (PMID 40473213, 2025).
colon carcinoma (continued). "By proteomic analysis, mutant KRAS colon cancer-derived EVs were discovered to transport mutant KRAS and other oncogenic proteins such as EGFR, SRC family kinases and integrins, toward neighbor cancer cells with wild-type KRAS, leading to enhanced growth of these neighbor cancer cells." (PMID 35927755, 2022). "Indeed, 249C potently inhibits tumor growth without adverse side effects in mouse xenografts of KRAS-driven lung and colon cancers." (PMID 35879364, 2022). "However, in malignancies with frequent mutations in the MAPK/ERK pathway, such as melanomas and colon cancers, the percentage of NRAS and KRAS mutation in Asians is not higher than those in Caucasians." (PMID 34063325, 2021). "Patients with no liver metastasis, KRAS wild type, and left colon tumor may be the beneficiaries of FP." (PMID 34692541, 2021). "To resolve whether or not the changes in the stromal gene signature expression were simply due to differences in the fraction of stromal versus cancer cells in KRAS‐mt vs KRAS‐wt tumors, we performed multiplex IF staining on KRAS‐wt (n = 23) and KRAS‐mt (n = 12) MSS colon cancer specimens." (PMID 33817986, 2021). "Other studies have shown that the low CBX7 expression was an independent predictor for poor prognosis in colon cancers, and the CBX7 negatively regulates KRAS through miR-155 to inhibit the anti-apoptotic activity, suggesting that CBX7 may play a role as an antioncogene." (PMID 33748425, 2021). "These drugs have proved to be ineffective against CRC; however, there may still be hope since FGTI-2734, a recently developed peptide inhibitor, can disrupt KRAS membrane localisation in various human cancer cell lines, including the DLD1 colon cancer cell line." (PMID 33802849, 2021). "Gene sets of mTORC1 signaling, KRAS signaling, and oxidative phosphorylation were also significantly enriched, which may unravel the process of cyclin genes (especially CCNB1) in colon cancer." (PMID 33996604, 2021). "Therefore, KRAS mediated oncogenic reprogramming does not seem to be involved in the altered NHEJ pathway in colon cancer." (PMID 33195430, 2020). "Moreover, KRAS G12D was shown to promote stronger colon cancer development than NRAS G12D in Apc-deficient mice, and HRAS G12V knock into the KRAS locus was not tumorigenic in the lungs of mice." (PMID 31941155, 2020). "Moreover, in KRAS WT patients, we found right colon cancer had worse CSS than left side colon cancer meanwhile in KRAS MT patients, there was no significant prognostic difference between right and left side colon cancers." (PMID 32547859, 2020). "No significant different between colon cancer and rectal cancer in the KRAS status (p = 0.393)." (PMID 30917791, 2019). "In colon cancer, ERMP1 is expressed irrespective of KRAS and /or BRAF mutational status." (PMID 27566589, 2016). "This agent has induced extensive cytotoxicity in human models of colon cancer, suggesting that GLI is a critical target in colon cancer cell survival, and in other cancers where GLI is constitutively activated and/or an oncogenic KRAS-GLI axis drives proliferation." (PMID 27863397, 2016).
colon carcinoma (continued). "Our findings suggest that BRAF600E and some KRAS mutant colon cancers are unlikely to respond to mono therapy targeting mTOR, but might benefit from combination therapy with BH3 mimetics, or inhibitors of PI3K, Raf or MEK." (PMID 27351224, 2016). "Because colon cancer cells with wild type KRAS could be transformed by WSTF/NRG3, they would be not sensitive to the targeted inhibition of EGFR." (PMID 27449290, 2016). "Due to the extensive cytotoxicity induced by GANT61 in human models of colon cancer, data suggest that GLI is a critical target in colon cancer cell survival, and also in other cancers where GLI is constitutively activated and/or an oncogenic KRAS-GLI axis drives proliferation." (PMID 24962990, 2014). "However, human colon cancer cell lines harboring mutant KRAS that did not respond synergistically to the combination therapy also did not exhibit any changes in phospho-Akt levels in response to treatment." (PMID 23555026, 2013). "Mutations of the KRAS gene are known to be negative predictive genetic markers for EGFR targeted therapy and were significantly associated with resistance to EGFR-blocking monoclonal antibody (cetuximab) in colon cancer." (PMID 24205362, 2013). "While such studies provide invaluable insights into oncogenic K-ras function, they do not provide insights into mechanisms that colon cancer cells with a wild-type KRAS may utilize." (PMID 20532039, 2010). "Furthermore, the current results indicate a role of mutations in KRAS, PIK3CA, and/or BRAF, and/or MMR deficiency in the etiological pathway between physical inactivity and colon cancer risk in women, but not men, and it seems that in particular PIK3CA mutations are involved in this association." (PMID 35546360, 2022). "Patients with no liver metastasis, KRAS wild type, and left colon tumor may benefit from FP." (PMID 34692541, 2021). "As migration and invasion of epithelial cells of the human colon (FHC cell line) in vitro was influenced by changing levels of FOSL2, we can hypothesize that regardless of the KRAS (wild-type or mutant), the sensitivity of colon cancer cells is influenced by the expression of FOSL2." (PMID 31245295, 2019). "One propagated tumor line, CBP1, from a model ES cell line overexpressing CDK14 in addition to β-Catenin was tested to assess whether a propagatable colon tumor lacking KRAS activation and CDK6 amplification would respond to either of the targeted agents or their combination." (PMID 25162504, 2014). "Tumors were absent in APC and KRAS mut mice not treated with DSS, while APC; KRAS mut mice developed small proximal colon tumors." (PMID 41285904, 2025). "Nevertheless, although they did not distinct rectal from left colon cancers in the comparative analysis, differences in PIK3CA and KRAS are correlative with ours, except the high proportion of KRAS also seen in rectal location within our population." (PMID 29632645, 2018). "Lastly, we recently demonstrated that the addition of 0.2 μM simvastatin (equivalent to the human cardiovascular dose) to cetuximab significantly enhanced antitumor activity in KRAS mutant colon cancer cells, but not in BRAFV600E mutant colon cancer cells." (PMID 23234464, 2012). "However, the identified SNVs are more promising than other biomarkers because, unlike SNVs in KRAS and BRAF, they target the entire colon cancer population, including rectal cancer, and are not rare like BRAF, nor are they expensive like circulating tumor DNA." (PMID 37784019, 2023). "Interestingly, quercetin produces a similar therapeutic effect for KRAS, HRAS, and NRAS oncoproteins, and their effect does not depend on the cell cycle position of colon cancer." (PMID 35409064, 2022). "Indeed, there are other important oncogenic pathways in colon cancer, such as WNT and EGFR, which interfere with the efficacy of KRAS (G12C) blockade, and KRAS inhibition alone does not appear to be sufficient to impede the oncogenic process." (PMID 34063682, 2021).
colon carcinoma (continued). "After removing studies that did not specifically separate rectal tumors from left‐sided tumors, the prevalence among left‐sided colon tumors did not change substantially from the original analyses (RAS: 36.4% vs 32.4%, KRAS: 34.7% vs 35.8%, BRAF: 4.4% vs 4.3%)." (PMID 31856410, 2020). "Towards this end, when PLX4720 was co-administered with TRAIL, in TRAIL sensitive DLD-1 cells, TRAIL induced apoptosis was abrogated indicating wild-type BRAF and not mutant KRAS, also present in DLD-1, as the exclusionary factor for colon cancer treatment with PLX4720." (PMID 21738740, 2011). "However, TAK1 dependency may not be restricted to colon cancer, and approaches in targeting TAK1 have shown activity in other KRAS dependent tumors as well." (PMID 33777798, 2021). "Metastatic colon cancers are routinely tested for mutant KRAS to determine suitability for biologic adjuvant therapy with the anti-epidermal growth factor receptor (EGFR) antibody, cetuximab, as surprisingly, patients with mutant KRAS fared worse with anti-EGFR therapy than without treatment." (PMID 26497569, 2015).